TNFAIP3 (TNF alpha induced protein 3)
Diseases named in the same sentence as TNFAIP3 in open-access papers (continued):
Sharing a sentence is not in itself a finding about the gene and the disease.
colon (1 paper, 2025). "Similarly, conditional deletion of A20, a suppressor of pro-inflammatory signaling pathways encoded by Tnfaip3, in CD11c+ cells, leads to early spontaneous colitis development in the SI and delayed colon inflammation after 6 months of age." (PMID 41028655, 2025).
epithelial carcinoma (1 paper, 2022). "The expression of TNFAIP3 was higher in immune cells, especially in epithelial carcinoma, macrophages, and CD8+ T‐cells (left), while TGFBI, IFI30, SPP1, and EREG were expressed more highly in macrophages than other cells." (PMID 35634956, 2022).
kidney (1 paper, 2022). "The present study showed that PGC-1α mitigated mitochondrial damage and oxidative stress levels, restored mitochondrial integrity and TNFAIP3, and attenuated the activation of the NLRP3 inflammasome pathway in the TGF-β-treated RTECs and animal models of kidney injury." (PMID 35013155, 2022).
TNFAIP3 also shares sentences with these, for which no sentence is quoted: autoimmune hepatitis (5 papers); ulcerative colitis (5); prostate carcinoma (4); ischemic stroke (3); neurologic disease (3); Allergy (2); Cervical Adenitis (2); chronic hepatitis B virus infection (2); chronic mucocutaneous candidiasis (2); depression (2); Hashimoto thyroiditis (2); inflammation (2); multiple myeloma (2); ovarian carcinoma (2); pharyngitis (2); Still’s Disease (2); triple-negative breast carcinoma (2); acute lung injury (1); acute myocardial infarction (1); adenitis (1); age (1); alcoholic liver diseases (1); Alzheimer disease (1); angiitis (1); angioedema (1); aphthous stomatitis (1); atopic dermatitis (1); autoimmune thyroiditis (1); brain diseases (1); cataract (1).
A further 85 diseases each share a sentence with TNFAIP3 in 1 paper.